CXCL10 (C-X-C motif chemokine ligand 10)
Diseases named in the same sentence as CXCL10 in open-access papers (continued):
Sharing a sentence is not in itself a finding about the gene and the disease.
infection (continued). "In particular, the gamma interferon (IFN- γ) inducible chemokines CXCL9, CXCL10, and CXCL11, and their receptor CXCR3, are involved in T cell and macrophage recruitment to the site of infection." (PMID 39301034, 2024). "CXCL10 and CXCL11 are proinflammatory chemokines that recruit immune cells, including monocytes and T cells, to the sites of infection or injury." (PMID 38638435, 2024). "These markers were better than plasma cytokine levels (such as CXCL10, IL-10) for differentiating MIS-C from infection controls." (PMID 38762592, 2024). "We examined secreted protein levels of IFN-β, CXCL10, CXCL11, CCL5, and IDO in two male and two female primary HLMVEC donors at 48 and 60 h post infection." (PMID 37766212, 2023). "Luminex analysis confirmed that remdesivir potently blocked SARS-CoV-2-induced cytokine release from ALI lung organoids at 48 hours post-infection, particularly evident for GCSF, IFNG, IL6, CXCL10, CCL2, and TNFA." (PMID 37205380, 2023). "The chemoattractant IP-10 (CXCL10) was also significantly increased compared to healthy controls (p < 0.0001) and moderate infection (p = 0.002)." (PMID 37598150, 2023). "It has been shown previously and in the present study that transcriptions of TNF, CXCL8, and CXCL10 in hBECs were induced upon A. fumigatus infection, which could help recruit neutrophils, phagocytes, and/or other immune cells to the sites of infection for fungal clearance." (PMID 37695039, 2023). "This was evidenced by significant, or close to significant, interactions between diet and infection for the expression of CXCL9, CXCL10, and TNF, indicating that infection-induced changes in gene expression were attenuated by inclusion of dietary Fer-SL." (PMID 38081984, 2023). "IP-10, known as CXCL-10, is an ELR‐negative CXC chemokine induced by IFN-γ or other stimuli during infection or inflammation in several immune cell." (PMID 36619224, 2023). "Hantavirus species comparative studies performed in HUVECs show similar gene expression profiles for CCL5 during HTNV and PHV infection, whereas both CXCL10 and CXCL11 transcript levels are expressed the highest following infection of HTNV followed by PHV." (PMID 37766212, 2023). "Following infection of BEAS-2B cells with RSV, we confirmed that RSV infection down-regulated miR-34b/c-5p, and up-regulated the expression levels of CXCL10 and CD14." (PMID 36829591, 2023). "Cytokines and chemokines in serum revealed an increase in the pro-inflammatory chemokines CXCL10 and CCL4 at week 4 post infection." (PMID 37837930, 2023). "The concentrations of chemokines, including CCL2, CCL5, and CXCL10, were all markedly reduced in the lungs of the AHCC-fed group at day 4 post infection (p < 0.05 or p < 0.01)." (PMID 37111440, 2023). "Infection by Alpha resulted in significant increase of several inflammatory cytokines such as CCL2, CXCL10 and IL-6 over a longer period of time compared to Ancestral strain." (PMID 37507719, 2023). "Expression of other genes that were strongly upregulated after infection with most mycobacteria included SERPINB1, CXCL2, CXCL8, CXCL10, and LCN2." (PMID 37822359, 2023). "In patients with infection confirmed at T3, both CXCL-9 and CXCL-10 levels were higher from T0 to T4." (PMID 37755950, 2023). "Recent studies have shown that Ly6Chi monocytes surround S. Typhimurium-confining granulomas in the spleen and recruit CD4+ T cells to the foci of infection by producing CXCL9 and CXCL10, both are ligands for CXCR3 expressed by Th1 cells." (PMID 37733817, 2023). "Following activation, virus-specific effector CD8+ T cells expand and migrate to the site of infection in response to chemoattractants CCL5 and CXCL10." (PMID 37896776, 2023). "At 4 dpi after Omicron BA.2 infection, newly-weaned hamster showed around 10-fold increase of IFN-α, IL-6, and TNF-α, and 4-fold increase of IFN-γ and CXCL10 in brain." (PMID 37122119, 2023).
infection (continued). "As an example, CXCL10 expression is important early in SARS-CoV-2 infection to create an antiviral environment, but later in infection, high CXCL10 and CXCL9 contribute to the cytokine storm that leads to severe disease." (PMID 37689116, 2023). "Similar to 12 h, genes significantly upregulated in the later stages of infection were cytokines or chemokines, such as CXCL1, CXCL2, CXCL3, CXCL8, CXCL10, and CCL20." (PMID 37211158, 2023). "qPCR assays showed that Ptk2b deficiency significantly attenuated the mRNA levels of Ifnb1, Ifit1 and Cxcl10 stimulated by HSV1-GFP and VSVΔM51-GFP infection." (PMID 37989995, 2023). "CCL2, CCL3, CCL5, CXCL10, and CCL10 are among the chemokines that drastically increased within 24 h and remained elevated after 48 h of infection." (PMID 35062368, 2022). "The proteomics and Luminex data showed that various macrophage and neutrophil related cytokines and chemokines like MCP-1, IP-10 (CXCL10), MIG, MIP-1β (CCL4), CXCL8 (IL-8), SAA2, and AXL were dramatically upregulated at 7 days after infection." (PMID 35903092, 2022). "Indeed, several key antiviral effectors and inflammatory drivers remained upregulated at late infection time points in older mice when compared to the 10 w-old animals, including several that were poorly upregulated initially in the older cohort; these included Il6, Isg15, Cxcl10, and Ifit2." (PMID 36415465, 2022). "This antigen-specific antibody-mediated infection was selectively coupled to chemokine ligand 5 (CCL5), interleukin 1β (IL-1β), and C-X-C motif chemokine ligand 10 (CXCL10) secretion and a reduction in granzyme B (GrB) release." (PMID 35862953, 2022). "Moreover, with the exception of il1b, signature genes of Cxcl10+ and Saa3+ monocytes were also upregulated in Ly6Chi monocytes from L. monocytogenes-infected mice, indicating a broad repertoire of putative new Ly6Chi monocyte subsets during this type of infection." (PMID 36010615, 2022). "The results from the ZIKV-infected astrocytoma cells were very similar to the results observed following CHIKV infection, with both CXCL10 and TNF-α robustly induced following infection." (PMID 35746681, 2022). "We confirmed a MDA5/STING-dependent upregulation of cytokine and chemokine genes after VACV∆C7L infection in AECII cells, including Ifnb1, Ccl2, Ccl7, Ccl4, Ccl5, and Cxcl10." (PMID 35351885, 2022). "Upon Tha and Th2P-4M infection, foetal pAstrocytes strongly induced the expression of IFIH1, CCL5, and CXCL10, whereas hiMicros strongly upregulated expression of CXCL10 and genes coding for antiviral proteins ISG15 and MX1." (PMID 36680128, 2022). "After PEDV-HBQY2016 strain infection, the expression levels of IL-1β, IL-6, MIP-1β, MCP-1, IL-8 and CXCL10 were significantly higher than those in in the control group." (PMID 36439802, 2022). "Consistently, the gene expression of Ifnb1, Il6, Cxcl10, and many ISGs was also reduced in BX795-pretreated cells during infection." (PMID 35604097, 2022). "In the current setting, transcript levels of the chemokines Cxcl10 and Ccl7 were also rapidly upregulated upon MCMV infection and reduced by TAT-I24 2 h post-infection." (PMID 35806257, 2022). "We detected CXCL10 and CXCL9 surges during primary infection to mirror NK cell, neutrophil and monocyte influxes." (PMID 35590057, 2022). "The first days of infection were characterized by a higher production of CCL2/MCP-1 and CXCL10/IP-10, which decreased as the infection progressed." (PMID 35456119, 2022). "The transcriptional changes upon infection were dominated by Ifng and its downstream genes (e.g. Stat1, Irf1, Fcgr1, Nos2, Cxcr3) and IFN-dependent CXCR3 binding chemokines (e.g. Cxcl9, Cxcl10)." (PMID 36400767, 2022). "MIG/CXCL9 and IP-10/CXCL-10, also named “interferon-inducible CXC chemokine receptor 3 ligands”, are ELR-negative CXC chemokines induced by IFN-γ or other stimuli during infection or inflammation in several immune cell." (PMID 36466710, 2022).
infection (continued). "Of note, infection with SARS-CoV-2 induces interferon-stimulated chemokines such as Cxcl9 and Cxcl10 similar to infected human lung." (PMID 34957381, 2022). "Proinflammatory cytokines and chemokines analyses in the BAL showed that VACV∆C7L infection resulted in the release of IFN-γ, IL-6, CCL2, CXCL10, and CXCL9 into the BAL." (PMID 35351885, 2022). "Expression of macrophage and neutrophil chemoattractants CXCL10, CCL3, CXCL1 and CXCL2 in the lung tissue were significantly lower in NOX4 TG mice compared to the WT mice at 3-days post infection." (PMID 35601109, 2022). "At the early stage of infection, IFN-β regulates the secretion of IP-10 (CXCL10), a chemokine that attracts NK cells." (PMID 35163035, 2022). "After 48 h of infection, the levels of TNF, CXCL8, IL6, CSF2, CD180, CD14, and CCL2 levels increased and those of IL-10, INFB1, and CXCL10 decreased." (PMID 36296238, 2022). "M1-type markers (iNOS, CXCL-10, and CD86) were significantly upregulated after infection, and the expression level of M2-type markers (CD206 and ARG1) did not change significantly." (PMID 36352407, 2022). "On the contrary, CXCL10 was more pronounced in the BMV, and both chemokines were progressively increased during the infection." (PMID 35027063, 2022). "In cRG-I supplemented groups, ex vivo stimulation of blood cells with poly-IC (a dsRNA analog) resulted in slightly more CXCL-10 prior to infection (NS) and a significant increase in CXCL-10 after infection." (PMID 36296939, 2022). "There was a significant increase in mRNA expression of macrophage and neutrophil chemotactic factors CXCL10, CCL3, CXCL1 (KC) and CXCL2 in the lungs of IAV-infected WT mice 3-days post infection." (PMID 35601109, 2022). "We found ΔM062R infection in these cells generally stimulated elevated IFN-I and ISGs, e.g., IFN β and CXCL-10, consistent with the previous screening results." (PMID 36103568, 2022). "SARS-CoV-2 infection also resulted in many cytokines and chemokines above baseline levels (all P < 0.05) throughout the infection, including IFN-γ, IL-1β, IL-4, IL-28, CXCL10, GM-CSF, LIF, CCL2, CCL7, MIP-1α, MIP-1β, RANTES, IFN-α, and IFN-β." (PMID 35634338, 2022). "Although serum CXCL10 and CXCL11 levels were negatively correlated with the potency upon infection, post-vaccination levels tended to be positively correlated in the recovered patient group." (PMID 36366324, 2022). "From the present investigation, we found the expression of IL-1β, CXCL10/IP-10 and CCL3/MIP-α increased in the blood and most organs day by day as the infection progressed." (PMID 35584087, 2022). "Infection with SARS‐CoV‐2 (MOI = 2) showed that knockdown of ZBP1 attenuated the expression of the measured cytokine genes, as well as the production of CXCL10 and to a lesser degree of IL‐6." (PMID 36268590, 2022). "The expression of CD11b, CD4, CD14, and CD68 for M0; IL-6, HLA/DRA, and CXCL10 for M21, and IL-10, CD163, fibronectin-1 or FN1, and CCL17 was evaluated by qPCR at 2 and 24 h after infection." (PMID 35889103, 2022). "The reduction of the mRNA expression of CCL2, CCL3, FGF, CXCL-10, and IFN-γ at the 9th-week post-infection reflects a downmodulation of the Th1 response by reducing the recruitment of inflammatory cells and HSCs to the granulomatous site." (PMID 35839247, 2022). "Analysis of cytokine and chemokines in serum showed a characteristic peak in IL-6, CCL2, CXCL10, and CXCL11 production at day 1 after virus inoculation as also described by others for H5N1 and pH1N1 infection." (PMID 33671829, 2021). "The amount of soluble CXCL10, CCL5, and IL6 was increased in the supernatant of infected astrocytes at 2 dpi, but it varies depending on the isolates used for infection similarly to the results obtained by RT-qPCR." (PMID 33407600, 2021).
infection (continued). "The present work expanded on these observations by demonstrating that infection with a DL isolate induced comparatively higher TNF, CXCL9 and CXCL10 expression than CL in cultured monocytes obtained from both CL and DL patients." (PMID 34568099, 2021). "Among the most notable differences were IL-6, CCL2, and CXCL10 (IP-10), at 4.1-, 2.3- and 2.1-fold higher levels, respectively, than those detected in response to the sublethal PVM infection." (PMID 33922096, 2021). "Inconsistent with the observed trend in the IFNB1 level, persistent upregulation of numerous ISGs, including CXCL10, MX1, and ISG15, was observed in response to SARS-CoV-2 infection from 3 to 7 days post-infection." (PMID 34104087, 2021). "IL-22 can act synergistically with TNFα in response to infection-promoting chemokine expression (including CXCL9, CXCL10 and CCL5) by human keratinocytes." (PMID 34207946, 2021). "At 24 h post-infection, serum levels of IL-6, IL-17A, TNF-α, and IFN-γ were greatly reduced in IL-38-treated group, CCL2 and CXCL10 decreased at day 4, IL-1β and CCL-5 decreased on day 7 in the IL-38-treated group compared with group without IL-38 treatment." (PMID 33414457, 2021). "The host cells (EA.hy926) responded to the infection with an increased gene expression of CCL5, ICAM-1, IL-6, and CXCL10." (PMID 34490828, 2021). "SARS-CoV-2 in vitro infection of patient PBMCs revealed impaired type I and III interferon responses and reduced CXCL10 expression, whereas production of proinflammatory cytokines were less affected, compared to healthy controls." (PMID 34531865, 2021). "Similar to our findings from the lethal infection model, treatment with L. plantarum resulted in significant reductions in the levels of immunoreactive IL-6, CCL2, and CXCL10 detected in the BAL fluid of mice inoculated with a sublethal dose of PVM." (PMID 34959580, 2021). "This is in line with our unpublished results, which demonstrate that ex vivo infection of vaginal explants with HSV-2 results in upregulation of not only IFN-λ but also several other immune factors, including CXCL9, CXCL10, IL-1α and TNF-α." (PMID 35126336, 2021). "The expression levels of CCL3, CCL5, CXCL10 and CX3CL1 in the brain tissue of infected mice was elevated with the extension of infection time." (PMID 34017692, 2021). "RV-C15 infection of naïve mice increased BAL monocytes, neutrophils, eosinophils and lymphocytes, while inducing mRNA expression of IFN-γ, CXCL10, IL-17A, IL-13 and IL-5." (PMID 33968043, 2021). "Nevertheless, MIG/CXCL9, IP-10/CXCL10, I-TAC/CXCL11, BLC/CXCL13 and JE/MCP-5/CCL2 detected in kidney of C3H-HeJ mice at 24h post infection was also detected in serum/blood cells in our study." (PMID 34249775, 2021). "Several chemokines were induced quickly in the early phase (day 2 p.i.)and maintained at a rather high level through the first week of infection, including CCL2, CCL3, CCL4, CCL7, CXCL10, IL-6, IFN-γ, CCL11, CCL5, TNF-α, CXCL1, IL-4, IL-12p70." (PMID 34379705, 2021). "As expected, MVA-infection strongly induced secretion of type 1 interferons (IFN-I) and the IFN-stimulated gene products CXCL10 and CCL5 in macrophages, as well as IL-6, TNF, and GM-CSF." (PMID 34711816, 2021). "WT-infection significantly upregulated the expression of gamma interferon (IFN-γ), IL-6, IL-10, and CXCL10 (also known as IP-10) in the lungs compared with that in S gene mutants." (PMID 34425707, 2021). "Upon znBAZ infection, CXCR3 ligands, CXCL-9, and CXCL-10 levels were significantly enhanced by 14- and 12-fold, respectively." (PMID 34305935, 2021). "Compared to sham treatment, RV-C15 infection significantly increased mRNA expression of IFN-γ, CXCL10, CXCL1, CXCL2, TNF-α, IL-12, IL-25, IL-13 and IL-5." (PMID 33968043, 2021). "Upon infection of WD-AECs with RSV-A2 or RSV-ON1-H1, the basolateral cytokine secretion revealed mainly CXCL10/IP-10 and CXCL8/IL-8 release." (PMID 34320038, 2021).
infection (continued). "Inhibition of miR-548d-3p reduced parasite growth early after infection and increased production of MCP1/CCL2, RANTES/CCL5, and IP10/CXCL10." (PMID 34178725, 2021). "There were some cytokine transcripts differentially expressed early in infection (IL6, CXCL10, and CCL3 for example), but overall only a minority of DEGs are cytokines (n = 13)." (PMID 34615921, 2021). "There was induction of a variable cytokine response in respiratory tissues at different days post-infection (dpi), including TNF-α, IFN-β, IL-4, IL-6, CXCL8 (IL-8), IL-10, IL-13, CXCL10 (IP-10), CCL5 (RANTES), CXCL9 (MIG), and CCL2 (MCP-1)." (PMID 34452505, 2021). "Thus, high levels of CXCL10/IP-10 may limit the spread of infection." (PMID 34578370, 2021). "Accordingly, we analyzed the expression of the chemokines CXCL9, CXCL10, and CXCL11 in unvaccinated and vaccinated mice of the strains C57BL/6, IL-23p19−/−, and IL-17A−/− after infection with Mtb via quantitative real-time RT-PCR analysis." (PMID 34351501, 2021). "The release of select inflammatory proteins (IL6, IL8, CSF3, IL1β, CXCL10, and ICAM1) into the culture medium of HEKs and SCC cells following infection with C. t." (PMID 31912662, 2020). "Upon fetal infection, a set of core responsive IFN-inducible genes (CXCL10, IFIH1, IFIT1, IFIT3, ISG15, and MX1) were strongly upregulated in both tissues." (PMID 33148169, 2020). "The four principal responses to mOVA2 infection of DCs in vitro, IFNα/β, CCL5, CXCL10, and IFNγ evident in the OT-I assay, also occurred in vivo." (PMID 31988324, 2020). "In order to analyze that, REX3 reporter mice (CXCL10-BFP and CXCL9-RFP) were infected and, on days 4, 9, 12, and 20 after infection, we quantified the number of those cells by flow cytometry." (PMID 32574175, 2020). "Production of IP10 (CXCL10), a common marker of a PRR response, was assessed in both cells types after infection with RNA and DNA viruses." (PMID 32102850, 2020). "We observed that both pDCs and MO-DCs produced CXCL10 chemokine (in purple) and interacted with CD8+ T cells (in red) during the infection with T. cruzi; however, the number of pDCs interacting with CD8+ T cells was higher than MO-DCs." (PMID 32574175, 2020). "One gene, C-X-C motif chemokine ligand 10 (CXCL10), showed an upregulated fold change in the PRRSV single infection that was approximately twice the expression of the coinfected group and three times that of the IBV group." (PMID 33187194, 2020). "Neutrophils are known to secrete cytokines and chemokines in response to infection neutrophils infected with H5N1 subtypes induced a trend of stronger gene transcription of TNF-α, IFN-β, CXCL10 and MIP-1α than that of H1N1 subtypes." (PMID 32576265, 2020). "Expression of chemokines involved in immune cell recruitment to tissue sites of infection, CCL5, CXCL10, CXCL9, and IL-15, were significantly lower in lung tissues of HTNV-infected Ifnar1-/- animals compared to WT controls." (PMID 32330200, 2020). "We found upregulated genes that were also upregulated following basolateral infection, such as CXCL2, CXCL3, CXCL10, IFNβ-1, IFNλ-1, -2, -3, endothelin 1 (EDN1) and IFIT-1, -2 and -3." (PMID 32872518, 2020). "At 70 h post infection, supernatants from cells infected with RST17 (CPAF-) had 48 pg/ml (88%) more CXCL10 than those infected with RST5 (CPAF+) (p < 0.001)." (PMID 33106516, 2020). "Several chemokines, including IP-10 (CXCL10), CCL2 (MCP-1), CCL3 (MIP-1α), CCL4 (MIP-1β), CCL5 (RANTES), and CCL7 (MCP-3) were also significantly increased upon infection." (PMID 32373101, 2020). "Reportedly, chemokines are specialized in the recruitment of various cells, including neutrophils (IL-8), monocytes (CCL2), Th1 cells (CXCL9, CXCL10), Th2 cells (CCL17, CCL21), and Th17 cells (CCL20), to sites of infection." (PMID 32231137, 2020).